MMP7 (matrix metallopeptidase 7)
Description:
Degrades casein, gelatins of types I, III, IV, and V, and fibronectin. Activates procollagenase.
Synonyms: MMP-7; MPSL1; PUMP-1
Tractability: Small molecule: an approved drug acts on it; a structure with a bound ligand is known; a high-quality ligand is known; it belongs to a druggable protein family. Antibody: UniProt places it where antibodies can reach, with high confidence; its Gene Ontology location is reachable by antibodies, with high confidence; UniProt predicts a signal peptide or a membrane-spanning region. PROTAC: a small molecule that binds it is known.
Target class: Metallo protease; Metallo protease M10A subfamily; Metallo protease MAM clan; Protease; Enzyme
Gene: Protein-coding gene on chromosome 11 (102,520,508 to 102,530,853, reverse strand). Ensembl gene ENSG00000137673.
Subcellular location: Secreted, extracellular space, extracellular matrix
Subcellular location (Human Protein Atlas): Nucleoplasm; Vesicles; Cytosol; Predicted to be secreted
Pathways (Reactome):
Extracellular matrix organization: Activation of Matrix Metalloproteinases; Assembly of collagen fibrils and other multimeric structures; Collagen degradation; Degradation of the extracellular matrix
Signal Transduction: Extra-nuclear estrogen signaling
Gene Ontology:
Molecular function: endopeptidase activity; metallopeptidase activity; protein binding; metalloendopeptidase activity; serine-type endopeptidase activity; peptidase activity; zinc ion binding
Biological process: membrane protein ectodomain proteolysis; membrane protein intracellular domain proteolysis; positive regulation of cell migration; proteolysis; collagen catabolic process; extracellular matrix disassembly; extracellular matrix organization
Cellular component: extracellular exosome; extracellular region; extracellular matrix
Genetic constraint (gnomAD): Loss-of-function variants: 22 observed, 28.68 expected, observed/expected ratio (o/e) 0.77, 90% interval 0.55 to 1.1. The upper end of that interval is the gene's LOEUF score, 1.1, which puts it in group 4 of 6, group 1 being the genes least tolerant of losing a copy. Missense variants: 338 observed, 314.48 expected, observed/expected ratio (o/e) 1.07, 90% interval 0.98 to 1.18. Synonymous variants: 134 observed, 121.62 expected, observed/expected ratio (o/e) 1.1, 90% interval 0.96 to 1.27.
Homologues: Orthologues: chimpanzee MMP7 (99% identical), macaque MMP7 (97% identical), pig MMP7 (82% identical), dog MMP7 (76% identical), rabbit MMP7 (75% identical), mouse Mmp7 (69% identical), rat Mmp7 (69% identical), tropical clawed frog mmp13 (48% identical), zebrafish mmp20a (40% identical), Caenorhabditis elegans zmp-3 (33% identical), Caenorhabditis elegans zmp-4 (24% identical), Caenorhabditis elegans Y50D7A.13 (19% identical), and 2 more. Paralogues in human: MMP2 (45% identical), MMP3 (45% identical), MMP12 (45% identical), MMP10 (44% identical), MMP20 (43% identical), MMP1 (42% identical), MMP15 (42% identical), MMP13 (42% identical), MMP27 (42% identical), MMP8 (41% identical), MMP25 (40% identical), MMP14 (39% identical), and 11 more.
Diseases named in the same sentence as MMP7 in open-access papers:
MMP7 is named in the same sentence as 380 diseases in open-access papers, as found by Europe PMC text mining. Sharing a sentence is not in itself a finding about the gene and the disease. The quoted sentences say what the papers report.
colon carcinoma (108 papers, 2004 to 2025). "MMP7 was highly expressed in colon cancer tissues and was associated with poor prognosis of patients." (PMID 38526326, 2024). "Further studies are needed to clarify the mechanism underlying the SDC2-prompted activating cleavage of pro-MMP-7 at the colon cancer cell surface." (PMID 35682569, 2022). "In the current study, we observed for the first time that AMPK activity was inversely linked to MMP-7 expression in colon cancer cells." (PMID 26116564, 2015). "Belonging to the MMP family, MMP-7 is overexpressed in many cancers including colon cancer and is associated with the metastasis and progression of cancers." (PMID 25136657, 2014). "The reduced spreading effect and cell motility caused by miR-139-5p in colon cancer cells was revealed to be associated with the inhibition of the protein expression of cell migration and invasion molecules MMP7 and MMP9." (PMID 24885920, 2014). "Additionally, MMP-7 is very closely associated with some of the prime factors in the tumorigenesis of colon cancer." (PMID 31200666, 2019). "If these changes occur in the earliest stages of colon cancer or precancer as we suspect, MMP-7 may be an excellent early diagnostic marker for colon cancer." (PMID 31200666, 2019). "In T1-tumors there was a strong association between MMP-7 and nodal metastases in colon cancer." (PMID 29731961, 2018). "Although matrix metalloproteinase (MMP)-7 expression is correlated with increased metastatic potential in human colon cancer cells, the underlying molecular mechanism of invasive phenotype remains unknown." (PMID 26116564, 2015). "In human colon cancer cells, BAs activate M3R, which stimulates interaction with the epidermal growth factor receptor through matrix metalloproteinase 7 (MMP-7) activation." (PMID 40218932, 2025). "Previous reports have shown that the PPARγ agonist troglitazone inhibits colon cancer metastasis by inhibiting matrix metalloproteinase-7 (MMP-7) synthesis and the adhesion of extracellular matrix (ECM) proteins." (PMID 39875357, 2025). "MMP-7 can predict a more aggressive phenotype of colon cancer and is inversely correlated with patient survival." (PMID 38911387, 2024). "In another study, tamoxifen and 5-Flurouracil (5-FU) alone, or in combination inhibited cell migration, proliferation and induced apoptosis and cell cycle arrest with downregulation of ERβ and matrix metalloproteinase 7 (MMP-7) in HT-29 colon cancer cells." (PMID 38372868, 2024). "Syndecan-2 enhances pro-MMP-7 processing and the subsequent cleavage of the E-cadherin substrate, enhancing colon cancer cell migration." (PMID 39153155, 2024). "MMP-7 can predict a more aggressive colon cancer phenotype and is inversely correlated with patient survival." (PMID 39247608, 2024). "Based on the current reports, we conducted a set of Western blots (WBs) to confirm that only colon cancer cells contain a large pool of MMP-7." (PMID 36831488, 2023). "For further analysis, we identified increased expression levels of VEGF-A, CTNNB1, CD44, and MMP7 oncogenic signatures in different colon cancer cell lines." (PMID 36672201, 2023). "Type 3 muscarinic receptor signaling promoted the migration and invasion of colon cancer cells via the activation of matrix metalloproteinase-7 (MMP-7) and epidermal growth factor receptor." (PMID 36077804, 2022). "We noticed that MMP-7 protein secretion was correlated with the invasion potential of colon cancer cells." (PMID 35740289, 2022). "Additionally, we studied whether TYMS overexpression would affect MMP-7, a small metalloproteinase known to be implicated in colon cancer development by decomposition of the extracellular matrix elements and basement membranes and activation of other MMPs such as proMMP-2 and proMMP-9." (PMID 35740289, 2022). "MMP-7 is the smallest MMP; its expression is associated with the development and metastasis of colon cancer." (PMID 35682569, 2022).
colon carcinoma (continued). "MMP-7 antisense oligonucleotides inhibit gene expression of MMP-7 and inhibit the metastasis of gastric and colon cancer by interfering with protein translation or promoting mRNA degradation." (PMID 36776395, 2022). "In summary, we herein reveal that mimetic peptides derived from SDC2 (e.g., S2-FE) can interrupt the interaction of SDC2 with pro-MMP-7 and thus suppress colon cancer cell activities." (PMID 35682569, 2022). "The results of the CPTAC dataset revealed that the protein expression level of MMP7 is notably higher in the primary tumor tissues of colon cancer, LUAD, and uterine corpus endometrial carcinoma (UCEC) than in the normal tissues (P < 0.001)." (PMID 35785154, 2022). "Lycopene can be used as a preventive agent because it decreases MMP-7 expression and inhibits the invasion of HT-29 human colon cancer cells." (PMID 35966890, 2022). "In colon cancer, FXR overexpression inhibits colon cancer cell proliferation and invasion in vitro by suppressing MMP7 mRNA and protein expression." (PMID 35563650, 2022). "For their model studies, they selected matrix metalloproteinase-7 (MMP-7) as a reliable biomarker enzyme for colon cancer detection found in serum." (PMID 36079250, 2022). "Because the extracellular domain of syndecan-2 is cleaved by MMP-7 in colon cancer cells, it is likely that MMP-7 is involved in syndecan-2 shedding when BFT contacts IECs." (PMID 34769248, 2021). "Further studies found the role of ATRA in inhibiting the MMP matrylisin (MMP-7) in colon cancer cells and in vivo animal model of colon cancer." (PMID 32012980, 2020). "Studies in multiple myeloma and breast and colon cancer detected specific proteases, including MMP-7, which is synthetized by the tumor cells, and is able to proteolytically remove the ectodomain of SDC1." (PMID 33114033, 2020). "In colon cancer group we observed that MMP-7 GG genotype as well as MT2A AG and GG genotypes were more frequent among cases than controls (18% vs 13.3 and 12.7% vs 7.3%, respectively)." (PMID 32765800, 2020). "Our work further connects high MMP-7 and MMP-9 expression to occludin degradation, loss of tight junctions and tumor cell budding in colon cancer." (PMID 29731961, 2018). "The expression of MMP7 has been reported to be upregulated in several kinds of cancer, including colon cancer, pancreatic cancer, breast cancer, gastric cancer, and esophageal cancer." (PMID 30428899, 2018). "miR-223 upregulation in a colon cancer cell line upregulated c-Myc, cyclinD1, MMP7, and vimentin expression, downregulated E-cadherin, increased nuclear expression of β-catenin, and enhanced RhoA activation." (PMID 28969027, 2017). "MMP7 was over-expression in colonic tumor tissue (P<0.05), showing the same results from both qRT-PCR and gene microarray analysis." (PMID 28796798, 2017). "Studies in colon cancer revealed that M3R was able to promote MMP7 to catalyze the release of HB-EGF and thus facilitate ACh-induced EGFR signaling activation." (PMID 28102288, 2017). "MMP7 displayed a significantly higher expression in the sera specimen of colon cancer patients in comparison with healthy control serum group (p = 0.003)." (PMID 27431388, 2016). "As we have observed for MMP7 and MMP10, we found that elevated abundance of serum MMP12 in colon cancer patients is associated with a significantly shortened overall survival." (PMID 27431388, 2016). "Our results indicate pro-tumorigenic effects of overexpressed MMP7 in colon cancer patients ́ sera compared to serum samples of a healthy control group resulting in significantly adverse overall survival." (PMID 27431388, 2016). "To further characterize MMP7 positive expressing colon carcinomas and to go insight a potential mechanism for MMP7 function in these tumours, we performed an expression analysis for MMP73 and putative coexpressed factors." (PMID 25596746, 2015).
colon carcinoma (continued). "These in vitro findings were further corroborated by clinical observations showing that MMP-7 was overexpressed in six out of eight colon carcinomas." (PMID 25823818, 2015). "In the current study, we observed that MMP-7 was differentially expressed in colon cancer cell lines, HT29, Caco2, SW620, and HCT 116, having different invasive potentials." (PMID 26116564, 2015). "In the current study, we investigated the regulatory effects of membrane NADPH oxidase (NOX) and AMP activated protein kinase (AMPK) on MMP-7 expression and invasive phenotype change in colon cancer cells." (PMID 26116564, 2015). "In this study, we clearly observed that the source of ROS governing MMP-7 expression in colon cancer cells was NADPH oxidase." (PMID 26116564, 2015). "For example, syndecan-2 can regulate the localization and activation of matrix metalloproteinase (MMP)-7, which is overexpressed in colon cancer." (PMID 25686828, 2015). "When PKP3 levels in normal colon samples were compared with that in colon cancer, the levels were found to be unchanged, while MMP7 levels were higher in colon cancer samples." (PMID 25875355, 2015). "Apart from ERK1/2, PI3-K and p38 have been involved in MMP-7 regulation in rat aortic vascular smooth muscle cells, human colon cancer and LOVO cells." (PMID 25823818, 2015). "An increase in the levels of MMP-7 mRNA was observed to correlate with increased dedifferentiation and metastasis in colon cancers." (PMID 25875355, 2015). "Overexpression of MMP-7 in human squamous cell carcinomas, in particular colon cancer cells, shows a strong positive correlation with metastatic potential of cancer cells." (PMID 26116564, 2015). "Increased cell migration was seen with wild-type (MMP-7-cleavable) syndecan-2, whereas a protease-resistant mutant triggered far less migration in human colon cancer cell lines and an animal model." (PMID 25686828, 2015). "Molecular switch from NOX1 to NOX2 in colon cancer cells induces ROS production and subsequently enhances MMP-7 expression by deactivating AMPK, which otherwise inhibits stimulus-induced autoregulation of ROS and NOX2 gene expression." (PMID 26116564, 2015). "MMP-7 overexpression drives colon cancer cells into an highly invasive phenotype through molecular switch from NOX1 to NOX2." (PMID 26116564, 2015). "In relation with this study, using antisense oligonucleotides to MMP-7 mRNA in human colon cancer cell line xenograft models showed inhibition of basement membrane penetration, and suppression of liver metastases." (PMID 24518611, 2014). "In SCID mice, inoculation with human colon cancer cells that overexpress MMP-7 increases tumor invasion and metastasis." (PMID 24518611, 2014). "One such example was noted with use of antisense oligonucleotides targeting MMP-7 mRNA, which prevented human colon cancer cell invasion in vitro by inhibiting expression of MMP-7." (PMID 24518611, 2014). "Further findings showed that radixin induced the activation of Rac1-ERK pathway, leading to an increase in MMP-7 production, thereby contributing to the invasion and migration of colon cancer cells." (PMID 25136657, 2014). "The expression of the secreted extracellular matrix-degrading proteinase MMP-7 has been shown to be upregulated by beta-catenin in colon tumor cell lines, and a crucial role prior to the onset of the invasive phenotype has been suggested." (PMID 22863036, 2012). "The expression of MMP-7 mRNA in all colon tumors and its correlation with depth of invasion/serosal involvement and lymph node metastasis were as well confirmatory." (PMID 22159423, 2012). "We chose HT29 cells because they express and secrete high levels of MMP-7 and express little MTG16 compared to other colon cancer cell lines, making them ideal for establishing repression of endogenous MMP-7." (PMID 23251453, 2012).
colon carcinoma (continued). "The current study determined the effect of sulindac treatment on MMP7 in the human colon cancer cell line, HT-29, and utilized a global approach to detect altered activities of other metallohydrolases." (PMID 21991341, 2011). "The present study indicated that sulindac sulfide is able to reduce the expression of MMP7 in the human colon cancer cell line HT-29 which was also observed, in vivo, in ApcMin/+ mice." (PMID 21991341, 2011). "Using q-PCR, immunohistochemistry and ELISA, we showed that H508 colon cancer cells express MMP7 and that MMP7 gene transcription is induced by bile acids." (PMID 24212649, 2011). "We found the best three single-gene discriminators for colon cancer are MMP7, DPT and MMP1 having 97.5%, 96.3% and 95.1% classification accuracy on the training set, and 97.9% and 90.9%, 97.9% and 74.6%, and 91.7% and 84.1% on the two test sets, respectively." (PMID 21060876, 2010). "The aim of the present study was to analyze the role of MMP7 and its cross-talk with the Fas/FasL system during the acquisition of oxaliplatin resistance in colon cancer cells." (PMID 19266094, 2009). "Our findings suggest that endocrine therapy is an efficient therapy for inhibiting ERβ-positive colon cancer cell proliferation and migration via down-regulation of MMP7." (PMID 19785773, 2009). "In left-sided adenocarcinomas, a first cluster (cluster I) of upregulated genes was observed containing PLA2G3 and several genes related to colon cancer such as HD-6, MMP-7 and Il-8." (PMID 18212756, 2008). "They showed that expression of the PEA3 Ets family, in conjunction with accumulation of β-catenin, leads to upregulation of MMP7 gene transcription in colon cancer." (PMID 15054469, 2004). "Additionally, retinoic acid has been shown to regulate Mmp7 homeostasis in lungs of asthma mouse model and healthy lungs in humans, as well as in human colon cancer and cancer cell lines." (PMID 36678247, 2023). "Moreover, cagA-dependent H. pylori increased MMP-7 in HT29 colon cancer cells and MMP-10 in gastric epithelial cells." (PMID 36014933, 2022). "Given that MMP-7 activity critically regulates the cancer activity of colon cancer cells, it is highly possible that both S2-D and S2-FE could act as anticancer agents." (PMID 35682569, 2022). "Notably, MMP7, has a well-documented role in colon cancer progression and metastasis, as does VEGF via vasculature remodeling in tumor-adjacent tissues." (PMID 35370785, 2022). "Although future studies will be required to clarify the underlying inhibitory mechanism and improve the stability of these peptides before they can be developed as new anticancer drugs, the present study lays new groundwork for the specific targeting of MMP-7 via SDC2 in colon cancer." (PMID 35682569, 2022). "Thus, the SDC2–MMP-7 interaction appears to be important for the enzymatic activity of MMP-7 in colon cancer cells." (PMID 35682569, 2022). "Notably, our group previously observed that M3R activation induces MMP7 expression in human colon cancer cells." (PMID 35370785, 2022). "Moreover, H2O2 induces activation of AP-1 in a JNK-dependent manner, leading to upregulation of matrix metallopeptidase 7 (MMP-7) and increased metastasis in human colon cancer cells." (PMID 35530337, 2022). "In addition, MMP7 is a biomarker associated with the epithelial-to-mesenchymal transition (EMT) of tumor cells that are highly invasive, as well as colon cancer and gliomas." (PMID 35954348, 2022). "Consistent with our data, it has been shown that the stimulation of LXR could down-regulate β-catenin targets such as Bmp4, Myc, Cyclin D1, and Mmp7 participating in the survival and proliferation of colon cancer cells." (PMID 33568147, 2021). "For example, isoproterenol might induce AP-1-mediated MMP-7 expression in gastric cancer cells, and hydrogen peroxide caused the expression of MMP-7 molecules in SW-620 human colon cancer cells via an AP-1 signaling pathway." (PMID 34769248, 2021).